KCNN4 (potassium calcium-activated channel subfamily N member 4)
Diseases named in the same sentence as KCNN4 in open-access papers (continued):
Sharing a sentence is not in itself a finding about the gene and the disease.
multiple sclerosis (10 papers, 2013 to 2025). A progressive autoimmune disorder affecting the central nervous system resulting in demyelination. "Modulation of the Kcnn4 channel represent a potentially therapeutic approach for skeletal pathologic conditions such as multiple sclerosis, inflammatory arthritis, and osteoporosis." (PMID 34279472, 2021).
Arrhythmia (9 papers, 2017 to 2025). Any cardiac rhythm other than the normal sinus rhythm. "The intermediate conductance calcium-activated K channels (KCNN4, SK4) are associated with arrhythmias in atrial fibrillation (AF) and CPVT." (PMID 36975511, 2023). "Of note, Kcnn4, upregulated in M1 macrophages, facilitates cardiac arrhythmias, regulating cardiomyocyte electrical conduction via gap junctions in the MI border zone." (PMID 35203431, 2022).
clear cell renal cell carcinoma (9 papers, 2015 to 2025). "In clear renal cell carcinoma increased expression of KCNN4 has been linked to shorter progression-free and overall survival, and a high metastatic potential." (PMID 39819494, 2025). "KCNN4 overexpression was related with low efficiency for ICIs in clear cell renal cell carcinoma." (PMID 38339019, 2024). "In addition, high KCNN4-mRNA levels were also associated with a lower overall survival, shorter progression-free survival, and a high metastatic potential of patients with clear cell renal cell carcinoma (ccRCC) suggesting that KCa3.1 may be of prognostic value in ccRCC." (PMID 30658505, 2019).
hepatocellular carcinoma (9 papers, 2014 to 2025). A malignant tumor that arises from hepatocytes. "Besides, aberrant expression of KCNN4 has been closely associated with papillary thyroid cancer, hepatocellular carcinoma, and colorectal cancer." (PMID 39282155, 2023). "In hepatocellular carcinoma, KCNN4 promoted invasion and metastasis in vitro by inducing the MAPK/ERK and EMT pathways." (PMID 32857728, 2020).
lung carcinoma (8 papers, 2016 to 2026). "Additionally, differential promoter methylation also causes epigenetic dysregulation in the KCNN4 locus in lung cancer." (PMID 36230742, 2022). "Notably, KCNN4 promoter hypomethylation is associated with high levels of SK4 in aggressively growing non‐small‐cell lung carcinoma cell lines and advanced stages of lung cancer in patients." (PMID 28557306, 2017). "Functional validation involved RNA interference targeting the KCNN4 gene in PC-9 lung cancer cells, including quantitative PCR, cell proliferation assays, wound healing assays, and Transwell invasion assays." (PMID 41741906, 2026). "In lung cancer, the calcium-activated potassium channel KCNN4 is significantly overexpressed in lung adenocarcinoma, where it regulates apoptosis and EMT via the PI3K/AKT and MEK/ERK pathways." (PMID 41155636, 2025). "Lung cancer studies included E3 (KCNK1), E8 (KCNK1, KCNN4), E12 (KCNH8, KCNMB2), E23 (KCNU1), E30 (KCNQ5-IT1), E35 (KCNK1), E43 (KCNK6), E49 (KCNN4), 2), E54 (KCNJ13), E63 (KCNK12), and E67 (KCNMB2)." (PMID 40867621, 2025).
colitis (7 papers, 2015 to 2023). Inflammation of the colon. "Recently, two studies with rodent models of colitis reported a decrease in disease severity after KCNN4 inhibition, which seems to contradict our hypothesis of beneficial effects of KCNN4 activation on mucosal healing under inflammatory conditions." (PMID 26824610, 2016).
myocardial infarction (7 papers, 2015 to 2022). Gross necrosis of the myocardium, as a result of interruption of the blood supply to the area, as in coronary thrombosis. "Furthermore, KCNN4 single-nucleotide polymorphisms have been related to myocardial infarction." (PMID 27716384, 2016). "Recent studies revealed that expression of KCNN4 is upregulated in macrophages recruited to the heart after myocardial infarction." (PMID 35812333, 2022).
Hypertension (6 papers, 2012 to 2021). The presence of chronic increased pressure in the systemic arterial system. "We revealed changes dependent on the hypertension model, since both KCNN4 and KCNN3 were downregulated in the aortas and mesenteric G3 arteries of SHR, whereas their expression levels were unchanged in DOCA-salt rats, with the exception of the KCNN4 level being enhanced in aortas." (PMID 34832902, 2021).
inflammatory bowel disease (6 papers, 2015 to 2023). A spectrum of small and large bowel inflammatory diseases of unknown etiology. "Furthermore, mRNA-levels of the potassium channel KCNN4 were determined in IEC from patients suffering from inflammatory bowel diseases (IBD)." (PMID 26824610, 2016).
colon carcinoma (5 papers, 2016 to 2024). "Enhancement of cellular proliferative ability in LoVo colon cancer cells is achieved through upregulation of intermediate conductance calcium-activated potassium channel protein 4 (KCNN4) expression in an NF-κB-dependent manner due to PRL-3 overexpression." (PMID 38540761, 2024). "An increase in wound healing following KCNN4-inhibition by Clt was reported previously in the human colon cancer-derived cell lines T84 and CaCo2, whereas the inhibitory effect of 1-EBIO could not be demonstrated in this study using a comparatively low concentration." (PMID 26824610, 2016).
epilepsy (5 papers, 2017 to 2021). A brain disorder characterized by episodes of abnormally increased neuronal discharge resulting in transient episodes of sensory or motor neurological dysfunction, or psychic dysfunction. "KCNN4, and RYR2) in proband with CAE and the father also has seizure disorder." (PMID 28074849, 2017).
lung adenocarcinoma (5 papers, 2016 to 2023). A carcinoma that arises from the lung and is characterized by the presence of malignant glandular epithelial cells. "Notably, this observation in patients is supported by findings in a model of A549 lung adenocarcinoma cells in which higher KCNN4 mRNA and KCa3.1 protein expression levels, as well as aggressive tumor cell behavior, were observed." (PMID 30658505, 2019).
triple-negative breast carcinoma (5 papers, 2016 to 2022). An invasive breast carcinoma which is negative for expression of estrogen receptor (ER), progesterone receptor (PR), and human epidermal growth factor receptor 2 (HER2). "For example, KCNN4 is highly expressed in triple-negative breast cancer and was found to promote the migration and EMT of triple-negative breast cancer cells." (PMID 32857728, 2020).
anemia (4 papers, 2016 to 2023). A reduction in the number of red blood cells, the amount of hemoglobin, and/or the volume of packed red blood cells. "Nonetheless, these KCNN4 mutations are associated with anemia that is often severe, especially in childhood and fetal life." (PMID 36003639, 2022). "The complete response observed under steroids, however, challenges the responsibility of the KCNN4 mutation alone in the pathophysiology of this transient anemia." (PMID 36003639, 2022). "The patients with KCNN4 mutations reported so far display a wide phenotypic heterogeneity, ranging from severe fetal anemia requiring in utero transfusions to mild or compensated hemolysis." (PMID 28496185, 2017). "The mutation H340N KCNN4 was correlated with a single episode of anemia which had not been further observed." (PMID 36003639, 2022). "Considering proband A (V222L mutation), the non-regenerative anemia may be due to either a non-identified intercurrent cause, or a role of KCNN4 during erythropoiesis, as described for PIEZO1-related DHSt." (PMID 36003639, 2022). "In contrast, proband A with V222L KCNN4 mutation exhibited a severe uncompensated anemia associated with major dyserythropoiesis that could not be explained genetically, but a defect in iron/heme metabolism has been suggested." (PMID 36003639, 2022).
colorectal cancer (4 papers, 2019 to 2025). A primary or metastatic malignant neoplasm that affects the colon or rectum. "In accordance with prior evidence suggesting a functional association between KCNN4 and KRAS signaling in colorectal cancer, our analysis revealed that KCNN4 expression is significantly elevated in KRAS‐mutant PDAC samples compared to wild‐type (Wilcoxon p = 3.5 × 10−16)." (PMID 40952239, 2025). "What’s more, evidence also shown that KCNN4 was upregulated by PRL-3 to promote the proliferation of colorectal cancer cells, and contributed to the invasion and metastasis of colorectal cancer by participating in the PRL-3 mediated EMT process." (PMID 37328854, 2023). "In addition, KCNN4 plays a role in the PRL-3-mediated EMT in colorectal cancer." (PMID 35098869, 2022). "Prognostic indicator based on TCGA colorectal cancer patients containing four key radiation resistance genes (LGR5, KCNN4, TNS4, CENPH) was established." (PMID 37328854, 2023). "Our data suggest that LGR5, KCNN4, TNS4 and CENPH are correlated with radiation sensitivity of colorectal cancer cells, and the indicator composed by them can reflect the prognosis of colorectal cancer patients undergoing radiation therapy." (PMID 37328854, 2023). "In conclusion, through the sorting and analysis of the radiation resistance projects in the GEO database and tumor vs. normal tissue project in TCGA-COREAD database, we established a gene panel (LGR5, KCNN4, TNS4 and CENPH) in colorectal cancer patients receiving radiotherapy." (PMID 37328854, 2023).
head and neck cancer (4 papers, 2021 to 2025). A primary or metastatic malignant neoplasm affecting the head and neck. "In head and neck cancer, the inhibition of programmed death receptor alpha 1 (αPD-1) increases the fluxes of KCNN4 and Kv1.3 channel activity, thus improving the immune function." (PMID 37408210, 2023). "Likewise, pembrolizumab, which is a humanized monoclonal antibody with high specificity towards PD-1, has been used in the treatment of several malignancies, including head and neck cancer, and increases KCNN4 channel activity and CD8 T-cell chemotaxis." (PMID 37408210, 2023).
hereditary xerocytosis (4 papers, 2020 to 2025). "For example, defects in the calcium activated Gardos channel (KCNN4) and the mechanosensitive cation channel (PIEZO1) are known to cause hereditary xerocytosis, an autosomal dominant hemolytic anemia." (PMID 33370780, 2020).
pancreatic ductal adenocarcinoma (4 papers, 2022 to 2025). An infiltrating adenocarcinoma that arises from the epithelial cells of the pancreas. "In pancreatic ductal adenocarcinoma, KCNN4 was reported to interact with GABRP to induce Ca2+ entry, which leads to the activation of NF-κB signaling and ultimately promotes macrophage infiltration." (PMID 35689211, 2022).
papillary thyroid cancer (4 papers, 2020 to 2025). "KCNN4 has been shown to modulate epithelial-mesenchymal transition and cell apoptosis, increasing the malignant behavior of papillary thyroid cancer cells." (PMID 35712127, 2022). "KCNN4 promotes papillary thyroid cancer cells progression via inducing epithelial-mesenchymal transition and restraining apoptosis, which suggests that KCNN4 may be a reliable diagnostic and prognostic biomarker for PTC patients." (PMID 35689211, 2022).
pulmonary disease (4 papers, 2008 to 2021). "Inhibition of KCNN4 is therefore likely to worsen CF-lung disease." (PMID 34066250, 2021).
renal carcinoma (4 papers, 2015 to 2025). A carcinoma arising from the epithelium of the renal parenchyma or the renal pelvis. "However, there is a certain positive correlation in renal cancer, that is, the higher the expression of KCNN4, the higher the drug sensitivity." (PMID 39282155, 2023). "Among 15 genes which downregulated in Ureteral sample, as well as the chromatin states closed in their potential regulatory sites, four genes (CEP170B, CHMP4C, KCNN4, and TJP2) are prognostic for renal cancer, that high expression is favorable." (PMID 40034749, 2025).
colonic adenocarcinoma (3 papers, 2015 to 2025). "A similar and robust association was observed in colon adenocarcinoma (COAD) cohort (p = 1.9 × 10−9), reinforcing the hypothesis of a conserved regulatory relationship between KRAS activation and KCNN4 expression across epithelial malignancies." (PMID 40952239, 2025).
cyst (3 papers, 2016 to 2025). A sac-like closed membranous structure that may be empty or contain fluid or amorphous material. "Since cyst expansion requires epithelial salt and water secretion likely involving basolateral membrane K+ recycling, we investigated the role of KCNN4-encoded K+ channel KCa3.1, inhibited by the potent, pharmacospecific, well-tolerated antagonist, senicapoc." (PMID 41122971, 2025). "Delayed cyst growth in Pkd1–/– metanephroi genetically deficient in Kcnn4 spurred in vivo studies of KCa3.1 function in mouse ADPKD models by generating Pkd1cko mice with inactivated Kcnn4 alleles." (PMID 41122971, 2025). "Our studies in Pkd1 mouse models demonstrate strong correlation of Kcnn4 expression status with cAMP/ERK/cMyc signaling in progression of cyst growth." (PMID 41122971, 2025). "We also evaluated renal Kcnn4 RNA expression in 2 transgenic ADPKD mouse models with slower cyst expansion and disease progression, SBPkd1 mouse and Pkd1wt." (PMID 41122971, 2025). "Genetic inactivation of Kcnn4 in rapidly and moderately progressive Pkd1 mouse models significantly delayed cyst growth, with substantial reduction in cellular, molecular, and physiologic hallmarks of PKD." (PMID 41122971, 2025). "We identified KCa3.1/Kcnn4 as a major contributor to cyst enlargement that is upregulated in human ADPKD kidneys and in kidneys of all examined Pkd1 mouse models." (PMID 41122971, 2025). "Semiquantitative histologic analysis of Pkd1cko;Kcnn4–/– kidneys revealed 20% reduction in cyst area and number versus Pkd1cko." (PMID 41122971, 2025). "The association was further supported by the selectively increased Kcnn4 expression relative to several other tested ion channels and transporters contributing to cyst fluid secretion." (PMID 41122971, 2025). "SBPkd1 kidneys (4 mo) exhibited increased Kcnn4 RNA signal versus WT, in cyst epithelial and surrounding cells with similar results in 6–7 mo Pkd1wt kidneys (not shown)." (PMID 41122971, 2025). "Pkd1–/–;Kcnn4–/– metanephroi exhibited ~40% lower cyst area and ~30% lower cyst number than in Pkd1–/–;Kcnn4+/+ metanephroi, suggesting that KCa3.1 expression contributes not only to cyst enlargement but perhaps also to cystogenesis." (PMID 41122971, 2025). "Conversely, reductions in cAMP, ERK, and c-Myc levels, along with decreased cyst growth upon Kcnn4 inactivation in PKD mouse models, revealed a molecular signature dynamically linked to cyst formation." (PMID 41122971, 2025). "Increased renal Kcnn4 RNA expression in cyst epithelium and surrounding tissue was consistent with contributory roles in cystogenesis and/or cyst enlargement." (PMID 41122971, 2025). "Kcnn4 is expressed at E14.5 and E16.5 in developing Pkd1+/+ or Pkd1–/– kidneys, validating cultured metanephroi as an ex vivo experimental system in which to investigate KCa3.1 roles in cyst formation and enlargement." (PMID 41122971, 2025). "Cyst area and cyst number were both lower in SBPkd1;Kcnn4–/– kidneys than in SBPkd1 kidneys." (PMID 41122971, 2025). "Genetic inactivation of Kcnn4 in Pkd1–/– metanephroi markedly delayed cyst initiation and growth." (PMID 41122971, 2025). "Prominent among the incompletely defined routes of basolateral K+ recycling in secretory epithelial cells and cultured ADPKD cyst epithelial cells is the KCNN4-encoded Ca2+-activated K+ channel of intermediate conductance, KCa3.1 (known in erythrocytes as the Gardos channel)." (PMID 41122971, 2025). "Notably, KCNN4 is responsible for calcium-dependent cyst fluid secretion and is thus a potential therapeutic target to inhibit cyst growth." (PMID 27871310, 2016). "Kcnn4 upregulation in 4 orthologous mouse models of ADPKD, together with KCa3.1’s role in ex vivo cyst enlargement, prompted our systematic assessment of several major effectors of the fluid secretion pathways driving cyst growth." (PMID 41122971, 2025).
cyst (continued). "Renal upregulation of Kcnn4 RNA is thus both reproducible and specific across multiple mouse models of ADPKD, supporting potential role(s) in cyst enlargement." (PMID 41122971, 2025). "P5 Pkd1cKO kidney sections revealed Kcnn4 RNA signal in noncystic tubules, with increased Kcnn4 signal in some cyst-surrounding cells and in interstitial regions." (PMID 41122971, 2025). "Although genetic inactivation of Kcnn4 and treatment with the KCa3.1 inhibitor senicapoc both slowed cyst growth, neither intervention eliminated cyst growth." (PMID 41122971, 2025).
liver fibrosis (3 papers, 2015 to 2020). "In addition to BK channels, intermediate-conductance Ca2+-activated K+ channels (KCa3.1, also known as KCNN4), have also been reported to be involved in the pathology of hepatic fibrosis." (PMID 32210801, 2020).
polycystic kidney disease (3 papers, 2014 to 2025). A usually autosomal dominant and less frequently autosomal recessive genetic disorder characterized by the presence of numerous cysts in the kidneys leading to end-stage renal failure. "Genetic and pharmacological inhibition of Kcnn4/KCa3.1 prevents or regresses cysts ex vivo, delays polycystic kidney disease in vivo and suggests a clinical trial candidate." (PMID 41122971, 2025).
viral infection (3 papers, 2010 to 2022). "Furthermore, 14 proteins that were upregulated after virus infection—including TNFaIP3, HNRNPH2, RSAD2, ISG20, IDO1, and KCNN4—also exhibited significantly increased mRNA levels relative to uninfected cells (p < 0.05)." (PMID 36423196, 2022).
common variable immunodeficiency (2 papers, 2019 to 2022). "Additionally, a patient of common variable immunodeficiency carried a KCNN4 gene hypermethylation, whereas its healthy monozygotic twin had no changes regarding KCNN4 methylation status." (PMID 30658505, 2019). "Epigenetically, KCNN4 is hypermethylated in memory B cells in common variable immunodeficiency (CVID) individuals relative to healthy individuals." (PMID 36275686, 2022).
cystic fibrosis (2 papers, 2015 to 2021). Autosomal recessive disorder caused by pathogenic variants in the CFTR gene (cystic fibrosis transmembrane conductance regulator), which encodes a chloride and bicarbonate channel expressed in epithelial cells, and follow the diagnosis criteria. "Thus, we would disagree with a recent report that claims inhibition of KCNN4 to reduce Na+ absorption and to improve mucociliary clearance in patients with cystic fibrosis." (PMID 34066250, 2021).
hereditary stomatocytosis (2 papers, 2018 to 2019). "Dehydrated hereditary stomatocytosis (DHSt) caused by PIEZO1 mutations was characterized by left-shifted curve, whereas KCNN4 mutations were associated with a normal curve." (PMID 29755372, 2018). "Though they satisfied those criteria, there are two possibilities that they have other forms of hemolytic anemia or other membrane gene mutations that is not included in our multi-gene panel (e.g. channel defects such as KCNN4 as found in hereditary stomatocytosis)." (PMID 31122244, 2019).
Hypokalemia (2 papers, 2023 to 2025). An abnormally decreased potassium concentration in the blood. "Nevertheless, KCNN4 channels promote the efflux of potassium, which is unlikely to cause hypokalemia." (PMID 37464309, 2023).
intestinal obstruction (2 papers, 2018 to 2020). Blockage of the normal flow of the intestinal contents within the bowel. "CftrΔF508/ΔF508/Kcnn4−/− double mutant mice are expected to show an increase in the occurrence of intestinal obstruction, and hence lethality with respect to single CF mice, due to an additional inhibition of calcium-activated secretion." (PMID 29915289, 2018). "Similar results are obtained in the CF CftrΔF508/ΔF508 mouse, which after Kcnn4 silencing, shows almost completely reduced lethality associated with intestinal obstructions, but this is not accompanied by improvements in intestinal anion secretion." (PMID 32814712, 2020).